SLC34A2 (solute carrier family 34 member 2)
Diseases named in the same sentence as SLC34A2 in open-access papers (continued):
Sharing a sentence is not in itself a finding about the gene and the disease.
mastitis (1 paper, 2024). Inflammation of breast tissue during lactation or postpartum due to an obstructed duct or infection. "Unbalanced Ca/P metabolism can induce mastitis in dairy cows, and solute carrier family 34 member 2 (SLC34A2) can affect transcellular inorganic phosphate absorption." (PMID 38731279, 2024). "In summary, we found that SLC34A2 can directly or indirectly regulate Ca/P metabolism and homeostasis and participate in the occurrence and development of clinical mastitis in dairy cows." (PMID 38731279, 2024). "In the present study, we found that SLC34A2 plays an important role in Ca/P metabolism and homeostasis, and is negatively correlated with the occurrence and development of clinical mastitis in dairy cows." (PMID 38731279, 2024). "The results revealed that SLC34A2 and DEPs could regulate Ca/P metabolism and homeostasis and participate in the occurrence and development of clinical mastitis in dairy cows." (PMID 38731279, 2024). "However, the specific role of SLC34A2 in regulating this imbalance in Holstein cows with clinical mastitis (CM) remains unclear." (PMID 38731279, 2024). "Previous studies have shown that DEPs, such as SLC34A2, PRKCB, FTH1, and MAPK1, could be putative biomarkers for mastitis." (PMID 38731279, 2024).
metastasis (1 paper, 2021). The spread or migration of cancer cells from one part of the body (where they first appeared) to another. "Thus, it can be inferred that high level of SLC34A2 both closely interrelated capsular invasion risk and extra-thyroid metastasis risk, whereas low SLC4A4 level was only closely related to the risk of extra-thyroid metastasis." (PMID 34405007, 2021).
mucinous tumors (1 paper, 2017). "The low expression of the target protein NaPi2b in the mucinous tumors correlates well with the low gene expression of SLC34A2 in this group." (PMID 28464843, 2017).
pancreatic cancers (1 paper, 2021). "Thereby, for these types of oncological diseases, the mutational profile of SLC34A2 can be a potential prognostic marker for breast and thymus cancers, and the upregulation of SLC34A2 can be a potential prognostic marker for brain, ovarian, and pancreatic cancers." (PMID 34944522, 2021). "The expression of SLC34A2 in pancreatic cancer has not yet been researched, and our study for the first time showed the correlation between patient survivability and SLC34A2 expression." (PMID 34944522, 2021).
pancreatic tumors (1 paper, 2021). "It was found that the life expectancy of breast and thymus cancer patients with an SLC34A2 mutation is lower, and it was revealed that SLC34A2 overexpression reduced the life span of patients with brain, ovarian, and pancreatic tumors." (PMID 34944522, 2021). "It was revealed that SLC34A2 mRNA overexpression decreases the lifespan of patients with brain, ovarian, and pancreatic tumors; therefore, the upregulation of SLC34A2 can be a prognostic marker for these tumors." (PMID 34944522, 2021).
serous ovarian carcinoma (1 paper, 2024). "Similarly, sodium-dependent phosphate transporter NaPi2b also known as SLC34A2, a sodium-dependent phosphate transporter, is overexpressed in high-grade serous ovarian carcinoma (HGSOC)." (PMID 40836974, 2024).
skin cancer (1 paper, 2021). "Our analysis for the first time showed that the expression of SLC34A2 is downregulated in skin cancer." (PMID 34944522, 2021). "The comparisons of SLC34A2 expression between healthy and tumor tissues showed a distinction in their expression level: upregulation was found in samples of myeloid, bowel, ovarian, and uterine tumors; downregulation was found in tumor samples of breast, liver, lung, and skin cancer tumors." (PMID 34944522, 2021). "Comparing the levels of SLC34A2 expression between relatively healthy and tumor tissues (Wilcoxon test, p < 0.05), the higher levels of expression were found in tumor tissues of the myeloid, bowel, ovary, and uterus, and the lower levels were found in samples of breast, liver, lung, and skin tumors." (PMID 34944522, 2021).
testicular germ cell tumor (1 paper, 2025). A germ cell tumor arising from the testis. "Testicular microcalcifications consist of hydroxyapatite and have been associated with an increased risk of testicular germ cell tumors (TGCTs) but are also found in benign cases such as loss-of-function variants in the phosphate transporter SLC34A2." (PMID 40279260, 2025).
thymoma (1 paper, 2021). A neoplasm arising from the epithelial cells of the thymus. "The result for the thymoma dataset indicated as significant only the presence of the mutation of SLC34A2 (HR = 24.57, CI: 1.87–323.65)." (PMID 34944522, 2021).
thymus cancer (1 paper, 2021). A primary or metastatic malignant neoplasm involving the thymus. "The results of the multivariate survival analysis showed that the mutational profile of SLC34A2 plays a significant role in the survivability of breast and thymus cancer patients." (PMID 34944522, 2021). "Our research, for the first time, showed the correlation between patient survivability and SLC34A2 alterations in thymus cancer." (PMID 34944522, 2021). "The analysis of the mutational data showed the lower life expectancy of patients with SLC34A2 alterations in the studies of breast and thymus cancers." (PMID 34944522, 2021).
uterine cancer (1 paper, 2021). Primary or metastatic malignant neoplasm involving the uterine corpus and/or the cervix. "The analysis of mutations in the SLC34A2 gene revealed that most of them are associated with skin, lung, bowel, and uterine cancer types." (PMID 34944522, 2021).
uterine tumors (1 paper, 2021). "The upregulation of SLC34A2 was found in samples of myeloid, bowel, ovarian, and uterine tumors; downregulation was found in tumor samples of breast, liver, lung, and skin cancer tumors." (PMID 34944522, 2021). "Furthermore, we suggest that SLC34A2 upregulation—not only for ovary but also for myeloid, bowel, and uterine tumors—can be considered as a potential predictive marker for targeted therapy with monoclonal antibodies, including XMT-1536 and XMT-1592." (PMID 34944522, 2021).
tumor (47 papers, 2005 to 2026). "The in silico analysis of 101,562 tumor samples performed during this study revealed 17 unique variants in the SLC34A2 gene leading to alterations in the amino acid sequence within the MX35 epitope (311–340 aa) of the NaPi2b transporter." (PMID 40265411, 2025). "Twenty-one functionally significant mutations in the SLC34A2 gene were found in two or more tumor locations." (PMID 34944522, 2021). "The most frequently occurring tumor locations (with the highest number of functionally significant mutations in the SLC34A2 gene) were the skin, lung, bowel, and uterus, with 23, 22, 17, and 17 unique mutations respectively." (PMID 34944522, 2021). "We observed that high expression of SLC34A2 was positively associated with larger tumor size (P=0.017; P=0.012, respectively) and advanced T status (P<0.001; P=0.008, respectively) both in training and validation cohorts of BC cases." (PMID 28151475, 2017). "In both two cohorts of BC samples, high expression of SLC34A2 was associated with large tumor size, advanced T status and poor patients' survival." (PMID 28151475, 2017). "We take this promotion of tumor growth as a potential underlying mechanism in SLC34A2-mediated BC carcinogenesis." (PMID 28151475, 2017). "One of the potential molecular tumor markers may be the sodium-dependent phosphate transporter NaPi2b encoded by the SLC34A2 gene." (PMID 34944522, 2021). "High SLC34A2 expression was found to be highly significantly associated with advanced tumor stage, positive capsular invasion, positive extrathyroid extension, large tumor size (>4 cm), and age ≥ 55 years (p ≤ 0.001 for each)." (PMID 34336552, 2021). "In the lung metastasis and H1299 subcutaneous tumor model, SLC34A2, a sodium-driven phosphate cotransporter, reduces tumor development and metastatic ability." (PMID 39170516, 2024). "Upon binding to the tumor antigen, these ADCs are internalized to release their cytotoxic payload with high specificity into tumor cells expressing SLC34A2." (PMID 40836974, 2024). "As reported in the literature, several studies have focused on OV, THCA, and LUAD, highlighting the positive correlation between SLC34A2 and tumor development." (PMID 37397501, 2023). "Our computational analysis showed that the SLC34A2 gene was upregulated in 15 tumor types when compared to pooled GTEx control group, especially in OV, THCA, and LUAD, whereas it was downregulated in 10, including COAD and BLCA." (PMID 37397501, 2023). "Sodium-dependent phosphate transport protein 2B (NaPi2b) is encoded by SLC34A2, which has been recognized to play a significant role in the regulation of tumor development." (PMID 38162667, 2023). "Future work should emphasize in vivo and in vitro gain- or loss-of-function experimental to validate these findings and further clarify which the major signaling pathway is regulated by SLC34A2 in tumor progression of PTCs." (PMID 34405007, 2021). "SLC34A2 has a dual nature, acting as both a tumor suppressor and a tumor promoter in a context-dependent manner and therefore exhibiting upregulation in some tumors and downregulation in others." (PMID 34336552, 2021). "RT-PCR results showed that expression of SLC34A2 mRNA was drastically up-regulated while SLC4A4 mRNA was drastically down-regulated in tumor tissue, when compared with the adjacent normal thyroid tissue (P all < 0.05)." (PMID 34405007, 2021). "Western blotting was used to determine the possible association between SLC34A2 and SLC4A4 protein expression with the p-ERK, p-JNK, and p-P38 protein expression in tumor tissues when compared to the adjacent normal thyroid tissue." (PMID 34405007, 2021). "All control samples of normal thyroid tissue (n = 238), as well as normal thyroid tissue adjacent to the tumor, showed low SLC34A2 IHC expression." (PMID 34336552, 2021). "To explore the underlying mechanisms of SLC34A2 in CRC cells, we employed array analysis of human tumor proliferation genes after knockdown SLC34A2 CRC cells." (PMID 30038060, 2019).
tumor (continued). "For example, SLC34A2 produces NaPi2b, a type II sodium-phosphate cotransporter that is highly expressed on tumor surfaces of NSCLC." (PMID 31434796, 2019). "The EJ/shSLC34A2 cells grew at a much slower rate than EJ/scramble cells, whereas SLC34A2 overexpression accelerated the xenograft tumor growth (P<0.001)." (PMID 28151475, 2017). "In contrast, miR-410 can accelerate tumor growth by suppressing the expression of SLC34A2, a type 2b sodium-dependent phosphate transporter (NaPi-IIb) that is located in the apical membrane of ATII cells." (PMID 28870231, 2017). "Taken together, these data indicate that SLC34A2 enhances tumor cell growth and proliferation through upregulation of c-Myc, which is a well-known oncogenic factor." (PMID 28151475, 2017). "The depletion of SLC34A2 in BC suppressed cellular viability, colony formation and anchorage-independent growth in vitro, and inhibited xenograft tumor growth in vivo, whereas overexpression of SLC34A2 had the converse effect." (PMID 28151475, 2017). "In conclusion, we report for the first time that SLC34A2, target of miR-218, is overexpressed pervasively in BC, and it is correlated with poor prognosis, advanced T stage and larger tumor size." (PMID 28151475, 2017). "We showed in vitro that knockdown of SLC34A2 blocked the effect of miR-410 inhibition, which were critical to tumor cell biology, namely, proliferation, migration and invasion." (PMID 26910912, 2016). "The mRNA expression levels of SLC34A2 were notably down-regulated in NSCLC tumor tissues compared with their normal counterparts." (PMID 26156586, 2015). "SLC34A2 also strongly inhibited tumor growth and metastasis ability in A549 subcutaneous tumor model and lung metastasis model, respectively." (PMID 26156586, 2015). "Two weeks after being injected with 3T3 cells transduced with either FIG-ROS(S), FIG-ROS(L) or SLC34A2-ROS(S), tumor formation was apparent in all the injected nude mice." (PMID 21253578, 2011). "Finally, SLC34A2 has been reported to exert a tumor-suppressive effect in NSCLC by attenuating tumorigenic potential and disease progression." (PMID 40787454, 2025). "Interestingly, we found that SLC34A2 was upregulated in immune-response (C2-C3) compared to immuno-quiet (C4-C6) signatures in tumor samples, suggesting its involvement into immunity activation." (PMID 37397501, 2023). "In some cancers, SLC34A2 is considered a potential prognostic marker of tumor disease." (PMID 37035196, 2023). "It is known that SLC34A2 might possess oncogenic or tumor-suppressive capabilities, therefore displaying different patterns of expression depending on cancer type." (PMID 34336552, 2021). "The present work revealed that higher SLC34A2 IHC expression was associated with poorer prognostic indicators of PTC, including older age, late tumor stage, larger tumor size, positive extrathyroidal extension, and positive capsular invasion (p ≤ 0.001 for each)." (PMID 34336552, 2021). "Moreover, none of the previous studies has assessed the possible role of SLC34A2 on tumor progression." (PMID 34336552, 2021). "The tumor samples were divided into groups in two ways: by the level of SLC34A2 mRNA expression and by the presence or absence of an SLC34A2 mutation." (PMID 34944522, 2021). "Another potential target, shared by the mouse and human tumor samples, is SLC34A2." (PMID 31940494, 2020). "Thus, we conclude that SLC34A2 enhances tumor cell growth and proliferation through upregulation of c-Myc, which is a well-known oncogenic factor." (PMID 28151475, 2017). "Furthermore, the average weight of tumor was significantly lower in the SLC34A2 depletion group compared with the EJ/scramble group (P<0.001), whereas overexpression of SLC34A2 in 5637 cells largely increased the tumor burden (P<0.001)." (PMID 28151475, 2017). "Notably, our analyses demonstrated that high level of SLC34A2 was significantly correlated with advanced T stage and larger tumor size." (PMID 28151475, 2017).
tumor (continued). "Moreover, SLC34A2 promotes BC cell proliferation and tumor growth both in vitro and in vivo, which is achieved via upregulating expression level and transcriptional activity of c-Myc." (PMID 28151475, 2017). "In addition, the expression of miR-410 was negatively correlated with that of SLC34A2 in human NSCLC tumor tissues." (PMID 26910912, 2016). "However, miR-410 expression levels were remarkably higher while SLC34A2 expression levels were significantly lower in 45 of 75 pairs of human NSCLC tumor tissues (45/75=60.0%) than that of their matched adjacent non-tumorous tissues respectively." (PMID 26910912, 2016). "Besides the Na+ dependent ileal bile acid transporter (Slc10a2) and Slc34a2, the sodium transporter Slc5a8, a tumor suppressor gene, was also more highly expressed in the ileum compared to the jejunum, but similarly expressed in the colon." (PMID 15882471, 2005). "Moreover, SLC6A14, SLC34A2, and SLC1A2 were linked to tumor immune responsiveness." (PMID 37397501, 2023). "In addition, 10 upregulated genes between the A549-P-S cell line stably expressing SLC34A2 and the control cell line A549-P were identified by microarray analysis and quantitative polymerase chain reaction, including seven tumor suppressor genes and three complement genes." (PMID 25017204, 2014). "Tumor tissues exhibited substantial upregulation of TFF1, UBE2C, ITPKA, and IGFBP3, alongside concurrent downregulation of SELENBP1 and SLC34A2, relative to matched normal samples." (PMID 40787454, 2025). "Contrasting with these findings, SLC34A2, a sodium-phosphate cotransporter downregulated in LUAD, functions as a tumor suppressor gene by maintaining calcium-phosphate balance." (PMID 40433361, 2025). "High SLC34A2 expression significantly correlated with important adverse clinicopathological parameters of PTC—i.e., late tumor stage, positive extrathyroid extension, tumor size > 4 cm, and age ≥ 55 years (p ≤ 0.001 for each)." (PMID 34336552, 2021). "In vivo, we found that, in the glucose group, xenograft tumors derived from si-SLC34A2 cells were markedly smaller than those from si-NC cells, whereas co-infected with p-EZH2 and si-SLC34A2 resulted in restored tumor volume." (PMID 30038060, 2019). "Fusion partners that participate in ROS1 rearrangements include CD74, SLC34A2, SDC4 in addition to GOPC/FIG, which was observed in this patient's tumor." (PMID 30719217, 2019). "In addition, survival analysis illustrated that SLC34A2 expression could significantly stratify OS in a subset of BC patients with different age, gender, T status, N status, overall clinical stage, tumor grade and tumor size." (PMID 28151475, 2017). "Thirdly, effects of SLC34A2 on NSCLC growth and metastasis ability were further identified with A549 subcutaneous xenotransplanted tumor model and lung metastasis model." (PMID 26156586, 2015). "The qRT-PCR results revealed pronounced upregulation of TFF1, ITPKA, UBE2C, and IGFBP3, along with marked downregulation of SLC34A2 and SELENBP1 in tumor samples relative to adjacent normal tissues, which was in strong agreement with the transcriptomic profiling outcomes." (PMID 40787454, 2025). "Interestingly, SLC6A14, SLC34A2, and SLC5A1 also resulted among the top DEGs SLC when comparing each TCGA tumor type with matched normal tissue." (PMID 37397501, 2023). "We noted that additional altered genes encode structural proteins such as membrane channels (e.g., APQ3) and transporters (e.g., SLC34A2 and NPC2) that may be coupled to key regulators in tumor cells." (PMID 33144684, 2021). "After adjustment for the other factors by backward stepwise Cox regression analysis, only lymph node status at presentation and tumor stage—but not SLC34A2 IHC expression—were identified as independent factors for OS." (PMID 34336552, 2021).
tumor (continued). "To determine the clinicopathological significance of the miR-410 and SLC34A2 aberration, we evaluated the mRNA expression of miR-410 and SLC34A2 in 75 pairs of frozen human NSCLC tumor tissues and adjacent non-tumorous lung tissues using qRT-PCR." (PMID 26910912, 2016). "Moreover, we found that miR-410 was significantly up-regulated and SLC34A2 was significantly down-regulated in 9 of 12 NSCLC tumor tissues compared with adjacent non-tumorous tissues simultaneously by qRT-PCR." (PMID 26910912, 2016). "Moreover, miR-410 or SLC34A2 alone was not statistically correlated to the clinical or pathological feature of tumor tissues as well (Data not shown)." (PMID 26910912, 2016). "Therefore, it can be hypothesized that the MAPK signaling pathway might act as a pivotal downstream (rather than upstream) signaling pathway for SLC34A2 and SLC4A4, to promote the tumor progression of PTCs." (PMID 34405007, 2021). "However, only a few studies have been conducted to evaluate the prognostic value of SLC34A2 in PTC, with none of them assessing its immunohistochemical (IHC) expression in a large cohort of patients with PTC or exploring its possible relationship with tumor progression." (PMID 34336552, 2021). "Therefore, the expression of miR-410 and SLC34A2 were conversely correlated, and the miR-410high/SLC34A2low expression signature frequently existed in human NSCLC tumor tissues but might not be correlated to the metastasis, differentiation or histopathological stage of NSCLC." (PMID 26910912, 2016).